LRP6 (LDL receptor related protein 6)
Diseases named in the same sentence as LRP6 in open-access papers (continued):
Sharing a sentence is not in itself a finding about the gene and the disease.
amyloid (4 papers, 2018 to 2021). "Secondly, expression of LRP6 is downregulated in AD brain, and deficiency in LRP6-mediated Wnt/β-catenin signaling contributes to synaptic dysfunction and amyloid pathology in AD." (PMID 31801553, 2019). "Common LRP6 variants are associated with late onset AD (see Section 4 and Section 4.1) while conditional Lrp6 loss of function in neurons elicited synaptic impairment in aged mice and exacerbated amyloid pathology in the APP/PS1 AD mouse model." (PMID 33255414, 2020).
coloboma (4 papers, 2009 to 2025). An abnormality in which a part of a structure in one or both eyes is missing. "Canonical Wnt signalling conveyed by β-catenin in the RPE cells is important for maintenance of dorsal identity in zebrafish retina, and inactivation of Lrp6, a co-receptor of canonical Wnt signalling, causes a defect in dorsal retinal patterning leading to a coloboma." (PMID 24324671, 2013). "Although the Lrp6−/− mice have microphthalmia with coloboma, they develop the basic structures of the eye: neural retina, RPE cell layer and the lens, which is in contrast to the β-catenin mutants presented in this work." (PMID 24324671, 2013). "In addition, knockout of LRP6 in mice resulted in microphthalmia and coloboma, but has not yet been reported in humans." (PMID 20057906, 2009).
esophageal squamous cell carcinoma (4 papers, 2020 to 2023). Esophageal squamous cell carcinoma (ESCC) is a type of esophageal carcinoma (EC) that can affect any part of the esophagus, but is usually located in the upper or middle third. "Here, we compared the expression level and function of LRP6 in CRC with that of esophageal squamous cell carcinoma (ESCC) bearing few Wnt/β-catenin pathway mutations." (PMID 36983771, 2023).
fatty liver disease (4 papers, 2014 to 2024). A reversible condition wherein large vacuoles of triglyceride fat accumulate in liver cells via the process of steatosis. "Additionally, mice carrying the loss-of-function mutation LRP6 p.R611C develop fatty liver disease including insulin resistance, liver inflammation, and steatosis due to increased hepatic de novo lipogenesis." (PMID 39037913, 2024). "Overall, the results from this acute overexpression study indicate that miR-182–5 p has a strong potential to worsen hepatic steatosis and possibly promotes insulin resistance and hyperinsulinemia via downregulation of LRP6." (PMID 39037913, 2024). "The knockout of LRP6, a receptor for canonical Wnt ligands, was shown to significantly induce liver steatosis through active hepatic AKT/PI3K/mTOR." (PMID 35800214, 2022). "Mechanistically, KAL induced hepatic steatosis and NASH by down-regulating ATGL and CGI-58 by LRP6/Gɑs/PKA/GSK3β pathway." (PMID 38472195, 2024).
glioblastoma (4 papers, 2020 to 2025). The most malignant astrocytic tumor (WHO grade IV). "The spearman’s correlation analysis of glioblastoma specimens demonstrated that LRP6 levels were inversely correlated with miR-137 expression levels in GBM samples (Spearman r = −0.565)." (PMID 33718112, 2020). "Recent research revealed that blocking the interaction between Wnt protein and their co-receptors such as LRP6 contributes to the anti-tumor effect in glioblastoma." (PMID 33718112, 2020).
glioma (4 papers, 2016 to 2026). A benign or malignant brain and spinal cord tumor that arises from glial cells (astrocytes, oligodendrocytes, ependymal cells). "As a member of the low-density lipoprotein receptor gene family, LRP6 has been recognized as an oncogene, which can be regulated by miRNAs in glioma." (PMID 33718112, 2020). "The overexpression of lncRNA PTCSC3 inhibits proliferation, migration and invasion of glioma cells and suppresses the Wnt/β-catenin signaling pathway through targeting LRP6." (PMID 28187755, 2017). "LncRNA PTCSC3 inhibits the proliferation and migration of glioma cells and suppresses Wnt/β-catenin signaling pathway by targeting LRP6." (PMID 28187755, 2017). "We have found that Wnt signaling is more active in gliomas compared with non-tumor regions, and LRP6 is also phosphorylated in GBM and GSC cells." (PMID 41141395, 2026). "Thus, we examined expression levels of the 19 Wnt ligands, 10 FZDs and co-receptors, LRP6, receptor tyrosine kinase-like orphan receptor 2 (ROR2), and receptor-like tyrosine kinase (RYK) in glioma spheres." (PMID 27698350, 2016).
non-alcoholic fatty liver disease (4 papers, 2014 to 2024). "Following we will describe our most pertinent findings related to Wnt/LRP6 regulation of de novo lipogenesis and adipogenesis and the role of impaired Wnt signaling in generation of ectopic fat, insulin resistance, elevated plasma lipids and non-alcoholic fatty liver disease (NAFLD)." (PMID 25526027, 2014).
Osteopenia (4 papers, 2010 to 2023). Osteopenia is a term to define bone density that is not normal but also not as low as osteoporosis. "Mice deficient in Lrp6 are characterized by osteopenia due to their inability to activate osteoblasts, and the expression of the mutant Lrp6 allele increases bone mass in mice." (PMID 37108563, 2023). "Mice lacking either Lrp5 or Lrp6 in mature osteoblasts displayed LBM and mice lacking both Lrp5 and Lrp6 in osteoblasts developed severe osteopenia." (PMID 29176883, 2017).
papillary thyroid carcinoma (4 papers, 2019 to 2023). "In papillary thyroid carcinoma, miR126 and miR381-3p expression inhibits cell proliferation, migration/invasion and reduces tumour growth by decreasing LRP6 expression." (PMID 31412666, 2019). "For example, LRP6 is a known target of microRNA (miR)-1271 in papillary thyroid carcinoma." (PMID 37873862, 2023). "Some evidence also suggests a role for LRP6 in the development of other epithelial cancers, including prostate, gastric, bladder, non-small-cell lung (NSCL) and papillary thyroid cancers." (PMID 31412666, 2019).
bladder cancer (3 papers, 2019 to 2024). "Interestingly, the single-nucleotide polymorphism of LRP6 rs10743980 was recently associated with a decreased risk of developing bladder cancer." (PMID 31412666, 2019). "Regarding bladder cancer, ectopic expression of LRP6 in T24 cells promotes viability and invasion, while knockdown of LRP6 induces cell apoptosis." (PMID 31412666, 2019). "The downregulation of Wnt pathway-related proteins such as Wnt5a/b, DVL2, LRP-6, and phosphorylated LRP-6 upon POLR3G knockdown was further confirmed by Western blotting, indicating that POLR3G may affect bladder cancer behavior through the Wnt signaling pathway." (PMID 39039528, 2024). "The downregulation of Wnt pathway-related proteins such as Wnt5a/b, DVL2, LRP-6, and phosphorylated LRP-6 upon POLR3G knockdown was further confirmed by Western blotting, indicating that POLR3G might influence bladder cancer behavior through the Wnt signaling pathway." (PMID 39039528, 2024).
breast tumor (3 papers, 2013 to 2021). "If antibodies that block LRP6-Wnt1 or LRP6-Wnt3a interactions are administered in mice, Wnt/β-catenin signaling is blocked and breast tumor growth is suppressed." (PMID 34589484, 2021). "Antibodies inhibiting the interaction of LRP6 with Wnt1 or Wnt3a decrease breast tumor growth in Wnt1- and Wnt3a-driven xenografts, respectively." (PMID 29854300, 2018). "We found that both LRP5 and LRP6 were more strongly expressed in TNBCs than in any other breast tumor subtype, consistent with published findings for LRP6." (PMID 29854300, 2018). "LRP5 and LRP6 although demonstrating a very similar expression profile within breast tumours have very different effects on recurrence." (PMID 23861811, 2013). "As a result, breast tumor metastasis, which is usually promoted by non-canonical Wnt signaling, is inhibited through the extracellular domain of LRP6." (PMID 34589484, 2021). "Therefore, LRP6 seems to play a dual role in breast tumor metastasis that depends on the presence or absence of Wnt." (PMID 34589484, 2021).
colitis (3 papers, 2021 to 2022). Inflammation of the colon. "It was recently reported that mice with IEC-specific deletion of Lrp6 are more susceptible to DSS colitis, and that enteroids derived from these animals exhibit reduced proliferation ex vivo." (PMID 34571979, 2021). "Consistently, it was recently shown that intestinal epithelial cell (IEC)-specific loss of Lrp6 increases the susceptibility to experimental colitis, and reduces enteroid growth ex vivo." (PMID 34571979, 2021). "Colorectal protein profile analysis showed that LRP6 expression was decreased in dextran sulfate sodium (DSS)-induced colitis mice, and mice received fecal bacteria transplantation from stroke patients." (PMID 35864969, 2022). "Results indicated that LRP6 was significantly decreased in the colon samples of mice with DSS-induced colitis and mice with fecal transplantation of stroke patients compared with control groups." (PMID 35864969, 2022). "For the treatment of colitis, drugs including AT-7519, curcumin (CU), SN-38, auranofin (AU), amsacrine, and emetine were used for the selection of LRP6 activators." (PMID 35864969, 2022). "Two drugs, curcumin and auranofin could alleviate intestinal barrier damage in DSS-induced colitis mice by targeting LRP-6." (PMID 35864969, 2022). "The mechanisms explaining this increased susceptibility to colitis in the absence of Lrp6 still need to be determined." (PMID 34359960, 2021).
colorectal tumor (3 papers, 2017 to 2023). "LRP6 phosphorylation is also increased in human colorectal tumours in comparison to healthy adjacent normal tissues." (PMID 31412666, 2019). "Above evidence suggested the possible role of LRP6 in promoting the migration in colorectal tumor cells." (PMID 29312635, 2017). "Moreover, LRP6 is hyperphosphorylated in KRAS-mutated cells and in patient-derived colorectal tumours." (PMID 31412666, 2019).
Crohn disease (3 papers, 2012 to 2023). A gastrointestinal disorder characterized by chronic inflammation involving all layers of the intestinal wall, noncaseating granulomas affecting the intestinal wall and regional lymph nodes, and transmural fibrosis. "For example, Crohn’s disease patients showed reduced HD5 and -6 levels, which were associated with decreased Tcf1, Tcf4, and LRP6, along with reduced Wnt signaling molecules Wnt1, -3, and -3a." (PMID 37762180, 2023).
fibrosis (3 papers, 2014 to 2025). the formation of excess fibrous connective tissue in an organ or tissue in a reparative or reactive process. "LRP6 overexpression reduced the expression and secretion of Wnt5a and Wnt11 by cardiomyocytes, and knockdown of Wnt5a and Wnt11 greatly inhibited cardiac fibrosis and dysfunction under pressure overload in vitro and in vivo." (PMID 33391533, 2021). "Although induction of Lrp6 was less in Ad vectors-induced fibrosis than bleomycin-induced fibrosis, induction of Wnt2, 2b, and 5b was comparable between these two fibrosis models." (PMID 25551570, 2014). "Cardiomyocyte-expressed LRP6 interacted with cathepsin D (CTSD, a protease) and promoted the degradation of Wnt5a and Wnt11, inhibiting cardiac fibrosis and dysfunction induced by TAC." (PMID 33391533, 2021).
Insulin resistance (3 papers, 2014 to 2024). Increased resistance towards insulin, that is, diminished effectiveness of insulin in reducing blood glucose levels. "Decreased IR expression and increased mTORC1 pathway activation, resulting in enhanced IRS1 serine phosphorylation due to the loss of TCF7L2 were found to be a cause of insulin resistance in patients with the LRP6-R611C mutation." (PMID 33969358, 2021).
ischemic stroke (3 papers, 2020 to 2022). A stroke disorder caused by obstruction of blood flow to the brain, due to thrombotic (local blood clot formation) or embolic (due to a blood clot or other material traveling from another site) event. "The Ischemic Stroke Genetics Study (ISGS) has identified some genetic variants in LRP6 to play a role in determining the risk of ischemic stroke." (PMID 33071819, 2020). "As has been reported, the mutations in LRP6 are associated with the risk of ischemic stroke; LRP6 protects the brain from ischemic injury, suggesting that LRP6 might provide a novel therapeutic approach for ischemic stroke." (PMID 35799601, 2022). "Meanwhile, the LRP6 expression was evaluated, and the data confirmed that LRP6 was lowly expressed in the blood samples of patients with ischemic stroke." (PMID 35799601, 2022). "As an essential member of the LRP family, LRP6 has been proved to exert an important regulatory function in the occurrence of ischemic stroke." (PMID 35799601, 2022). "LRP6 is a single-span transmembrane protein and is involved in the regulation of various disease processes, including ischemic stroke." (PMID 35799601, 2022). "Based on these findings, we further confirmed that miR-29c-5p bound to LRP6, and the expression of LRP6 in astrocytes was negatively regulated by miR-29c-5p, and LRP6 was lowly expressed in clinical blood samples from patients with ischemic stroke." (PMID 35799601, 2022). "This study might provide a novel regulatory axis for ischemic stroke: miR-29c-5p/LRP6." (PMID 35799601, 2022). "Thus, our study might provide a novel regulatory axis for ischemic stroke: miR-29c-5p/LRP6." (PMID 35799601, 2022).
lymph node metastasis (3 papers, 2017 to 2025). "Additionally, increased expression of phosphorylated LRP6 (p-LRP6) was significantly associated with deeper tumor invasion (T3/T4) and the presence of lymph node metastasis." (PMID 40943055, 2025). "76.6% (59/77) of cases with lymph node metastasis was positive p-LRP6, but only 48.8% (39/80) (p<0.001, χ2=12.995) without metastasis showed p-LRP6 expression." (PMID 29312635, 2017). "Further, LRP6 immunoreactivity was more intense in tumor with lymph node metastasis (t-test; with node metastasis N=9, without node metastasis N=19; P=0.0206)." (PMID 28880263, 2017).
myocardial ischemia (3 papers, 2021 to 2022). A disorder of cardiac function caused by insufficient blood flow to the muscle tissue of the heart. "In addition, injection of DKK2, an antagonist of Wnt signaling, binding to LRP5 and LRP6, was shown to be beneficial for infarct healing in a cardiac ischemia/reperfusion model." (PMID 34205318, 2021).
ovarian carcinoma (3 papers, 2016 to 2023). A malignant neoplasm originating from the surface ovarian epithelium. "Among the targets identified here, PCHDB15 was homogeneously expressed in 100% of patient samples, followed by LRP6, with more than 90% of tumours expressing the target in more than 75% of ovarian cancer cells." (PMID 37873862, 2023). "Of paramount significance, we identify three promising ovarian cancer targets suitable for ADC development: LRP6, PCDHB10, and PCDHB15." (PMID 37873862, 2023). "Interestingly, the antibody targeting LRP6 also exhibited a higher dissociation rate (high kd value) while internalising to greater levels in ovarian cancer cells, which warrants future investigation." (PMID 37873862, 2023). "In this context, ADC targeting of LRP6 could be a promising approach in ovarian cancer but could also extend its translation as therapeutic for other cancer types." (PMID 37873862, 2023). "It has been shown that LRP6 silencing in ovarian cancer leads to a decrease in chemoresistance." (PMID 37873862, 2023). "LRP6 mRNA levels were significantly upregulated in ovarian cancer cells compared to healthy ones." (PMID 37873862, 2023). "Additionally, the LRP6-mediated Wnt pathway is significant in ovarian cancer progression due to its ability to promote cancer stemness and metastasis, the latter being a major feature in ovarian cancer." (PMID 37873862, 2023). "Niclosamide, an FDA-approved anthelmintic, suppresses ovarian cancer stem cell proliferation by blocking the Wnt/β-catenin signaling via DVL2 and LRP6 inhibition." (PMID 36185280, 2022). "They suppressed LRP6 expression, inhibited both Wnt/β-catenin and mTOR/STAT3 signaling in ovarian cancer ascites cells and chemoresistant cell lines, and displayed potent in vitro anti-proliferative effects." (PMID 27888804, 2016).
pulmonary fibrosis (3 papers, 2012 to 2025). Chronic progressive interstitial lung disorder characterized by the replacement of the lung tissue by connective tissue, leading to progressive dyspnea, respiratory failure, or right heart failure. "Studies in animal models, as well as in human disease, have identified several components of the canonical WNT signaling pathway, including WNT2, FZD7, LRP6, β-CATENIN and GSK-3β which are overexpressed in idiopathic pulmonary fibrosis (IPF)." (PMID 22846383, 2012).
spina bifida (3 papers, 2018 to 2023). A congenital neural tube defect in which vertebrae are not fully formed. "Another prominent phenotype in mice carrying either gain-of-function or loss-of-function mutations of Lrp6 is neural tube defects (NTDs) with full penetrance of spina bifida and incomplete penetrance of anterior neural tube closure defects causing exencephaly." (PMID 37091972, 2023). "We also screened for other PCP genes including CELSR1, SCRIB, and LRP6 in the 192 US spina bifida, but no double PCP damaging missense variants were found in our current analysis." (PMID 30689296, 2019). "Case NTD_15 with LRP6 p.Arg386Cys and CELSR1 p.Arg714His had both anencephaly and spina bifida." (PMID 29618362, 2018).
adenoma (2 papers, 2017 to 2021). A neoplasm arising from the epithelium. "As expected, LRP6 is dispensable for adenoma formation in ApcMin/+ mice and for growth of human CRC cells in culture." (PMID 34359960, 2021). "Comparing to non-neoplastic glandular cells (4.8%, 1/21) and adenoma tissue (5.3%, 2/38), the expression of p-LRP6 was much more intense in carcinoma with higher positive level (62.3%, 114/183), which displayed the significant statistical difference (p<0.001)." (PMID 29312635, 2017).
Arrhythmia (2 papers, 2016 to 2021). Any cardiac rhythm other than the normal sinus rhythm. "The deficiency of LRP6 is associated with a high risk of arrhythmias." (PMID 35187114, 2021).
cardiac hypertrophy (2 papers, 2021). "LRP6 overexpression inhibited β-catenin activation in CMs, likely resulting in cardiac hypertrophy inhibition under pressure overload." (PMID 33391533, 2021). "The results indicated that leupeptin showed few cardiac hypertrophy effects in LRP6-overexpressing hearts or the MCM group after TAC." (PMID 33391533, 2021). "Cardiomyocyte-specific LRP6 overexpression improved cardiac function and inhibited cardiac hypertrophy and fibrosis four weeks after TAC." (PMID 33391533, 2021). "Furthermore, our study revealed that LRP6 inhibited β-catenin activation, which may be related to the reduced cardiac hypertrophy in LRP6-overexpressing mice under pressure overload." (PMID 33391533, 2021). "Cardiac LRP6 overexpression inhibited cardiac hypertrophy and fibrosis but did not promote autophagy after pressure overload (data not shown)." (PMID 33391533, 2021). "However, leupeptin did not affect cardiac hypertrophy in LRP6-overexpressing mice under pressure overload." (PMID 33391533, 2021).
cardiomyopathy (2 papers, 2018 to 2021). A disease of the heart muscle or myocardium proper. "Low-density lipoprotein receptor-related protein 6 (LRP6) is involved in the process of cardiomyopathy." (PMID 34712388, 2021).
chronic lymphocytic leukemia (2 papers, 2012 to 2016). "In chronic lymphocytic leukemia cells, Salinomycin inhibits the Wnt signaling cascade by blocking the phosphorylation of the Wnt co-receptor lipoprotein receptor related protein 6 (LRP6) causing impaired cell survival." (PMID 23057720, 2012). "Reduced phosphorylation of LRP6 after exposure to Sal was first described in chronic lymphocytic leukemia cells." (PMID 27855654, 2016).